CCL5 (C-C motif chemokine ligand 5)
Diseases named in the same sentence as CCL5 in open-access papers (continued):
Sharing a sentence is not in itself a finding about the gene and the disease.
tumor (continued). "RFP-labeled A2780-derived NCSLCs alone, or NCSLCs mixed with CSLCs transduced with lentivirus carrying CCL5-shRNA, or lentivirus control, were injected i.p. into recipient mice, and tumor metastasis was then evaluated by in vivo imaging." (PMID 25788271, 2015). "Through the inhibition of CCL5 expression, our study has for the first time discovered the causal role of RKIP in modulating tumor microenvironment by disrupting the communication between cancer cells and macrophages." (PMID 26375811, 2015). "CCR5 receptor is functional since human recombinant CCL5 increases the clonogenic growth of cHL tumor cells." (PMID 24523569, 2014). "The investigation of the roles played by CCL5/CCR5 in tumor development and metastasis is only in its infancy." (PMID 24523569, 2014). "Disruption of CCR5 signaling in the tumor slows tumor growth through a Treg-mediated mechanism, although disruption of the CCL5/CCR5 axis skews migration of only about 20% of the CD4+ population (less Tregs, more Teffs)." (PMID 24591756, 2014). "CCL5 is a key target of miR-214 and the downregulation of miR-214 increases CCL5 production, leading to increased tumor growth." (PMID 24523569, 2014). "Both CCR5 and CCL5 are also constitutively expressed by cHL-derived cell lines (L-428, KM-H2, L-1236, and L-540), by tumor cells from cHL lymph node tissues, and by bystander cells including lymphocytes and macrophages." (PMID 24523569, 2014). "CCL5 is also present in interstitial fluids perfusing the tumor, in pleural effusions, and in serum." (PMID 24523569, 2014). "In this tumor the major source of CCL5 is the tumor cells; however, CCL5 is also expressed by infiltrating leukocytes and mesenchymal stem cells (MSCs) of the tumor microenvironment." (PMID 24523569, 2014). "In another study, it has been shown that a CCL5 (RANTES) expressing oncolytic vaccinia virus significantly improved the therapeutic efficacy of a tumor-directed DC-vaccine." (PMID 25101244, 2014). "A variety of immunocytes have strong chemotactic effects after being regulated upon the activation of normal T-cell expressed and secreted RANTES/CCL5 that chemotactically attracts a huge number of immunocytes to tumor tissues to exert antitumor efficacy." (PMID 23292657, 2013). "Further researches gave the indication that CCL5 produced by tumor cell-stimulated MSCs, through binding with CCR5, lead the tumor metastasis." (PMID 23336752, 2013). "The decrease in CCL5 was reversed by the PGE2 receptor antagonist consistent with a report showing that tumor-secreted PGE2 inhibits CCL5 production in macrophages." (PMID 24025197, 2013). "Tumor cells induced expression of CCL5 (regulated and normal T cell expressed and secreted; RANTES) in MSCs, which in turn increased tumor migration and metastasis in a paracrine and/or endocrine manner." (PMID 23744479, 2013). "Disruption of CCR5/CCL5 signaling has also been shown in mouse models to impair intra-tumoral Treg accumulation and slow tumor progression." (PMID 23874342, 2013). "The inhibitory effects of tumor-secreted PGE2 on macrophage CCL5 are mediated through cAMP further supporting the idea that inhibitory effects of saliva on macrophage cytokine secretion are caused by PGE2 and mediated through cAMP." (PMID 24025197, 2013). "Following injection of these T cells the CCR5+ dendritic cells were recruited into the tumor microenvironment by CCL5 and elicited a prolonged endogenous anti-tumor response." (PMID 24384839, 2013). "After we confirmed that CAF-related SDF-1/CXCR4 and TAM-related CCL5/CCR5 expressions were changed under different ZHENG conditions, we next investigated an association between the altered tumor microenvironments and tumor growth." (PMID 22690248, 2012). "Here we found that CCL5 increased αvβ3 integrin expression by using flow cytometry analysis, which plays an important role during tumor metastasis." (PMID 22506069, 2012).
tumor (continued). "Increases measured in the levels of CCL5 (RANTES) secreted by the pro-tumor MSC2 groups are in agreement with previous reports." (PMID 23029122, 2012). "In the murine model for breast cancer, macrophages were recruited by the tumor cell-derived chemokine CCL5." (PMID 22778768, 2012). "After treatment with the receptor antagonist met-CCL5, both the number of infiltrating macrophages and the size of the tumor were significantly reduced." (PMID 22778768, 2012). "In carcinomas monocytes can be recruited by e.g. CCL5 and CSF-1 expressed by tumor cells and this tumor infiltration of monocytes contributes to the tumor-promoting inflammatory response in the cancer." (PMID 22992343, 2012). "Combined with GCV, the administration of CCL5/HSV-TK+ MSCs led to significant reduction in tumor mass." (PMID 22952657, 2012). "Major attractants of monocytic cells are the CC chemokines and in a variety of cancers, CCL2 and CCL5 levels are highly correlated with high numbers of intra-tumor myeloid cells, particularly TAM." (PMID 24212934, 2011). "Elevated levels of CCL5 expression were detected in all tumor models (subcutaneous, hepatic and lung) developed with mouse CT26 cells and with human HT29 cells except in pulmonary lesions derived from CT26 cells." (PMID 22205974, 2011). "It is therefore possible that simultaneous disruption of CCL5/CCRs axes potentiates this effect on the vasculature by reducing the immune tolerance towards tumor cells." (PMID 22205974, 2011). "Previously, it was shown that 4T1 cells produce various chemokines, including CCL2, CCL3, CCL4 and CCL5, that we also detected in the tumor microenvironment, with CCL5 levels being significantly higher in tumors in α-TEA-treated mice." (PMID 21232138, 2011). "Together, these findings indicate that there was high incidence of CCL2, CCL5, TNFα and IL-1β expression in the tumor cells in the three groups of cancer patients, and that the expression of TNFα and IL-1β was further elevated in the IDC-with-relapse group." (PMID 21486440, 2011). "Accordingly, the protective effect of TAK-779 against tumor development in mice was much less pronounced than that of CCL5 blockade." (PMID 22205974, 2011). "Selective targeting of the CCR5/CCL5 signaling also led to reduced tumor growth in experimental pancreatic adenocarcinoma through disruption of CCR5-dependent recruitment of regulatory T cells into tumors." (PMID 22205974, 2011). "Because CCL5 acts through specific receptors, we also looked for such receptors that were expressed within tumor and metastatic specimens." (PMID 22205974, 2011). "Proliferative and migratory responses of the tumor cells from human and mouse origins to CCL5 were significantly reduced by TAK-779, thus implicating CCR5-mediated processes in the direct stimulatory effects of CCL5 onto CRC cells." (PMID 22205974, 2011). "Our analysis of differential expression between adjacent stroma and tumor epithelia showed that the cytokines, CCL5 and CXCL 13, and the growth factors, IGF-1 and FGF-2, were upregulated in stromal cells." (PMID 20426842, 2010). "In the tumor microenvironment (TME), the dualistic nature of chemokines was highlighted: tumor-associated macrophages (TAMs) could secrete immunosuppressive factors, such as CCL22 and CCL5, recruiting inhibitory cells and inducing CD8+ T cell exhaustion." (PMID 41635851, 2026). "Taken together, this work reveals a critical host-protective role for miR-146a in HCC that is mechanistically dependent on CCL5 and wherein tumor burden correlates with two suppressive immune populations, providing an impetus for targeting these pathways to combat HCC." (PMID 41718085, 2026). "The elevation of CCL5/RANTES levels in patients with PTC in our study may be attributed to several factors related to the tumor microenvironment and immune response dynamics." (PMID 40150133, 2025). "Finally, we constructed a 4T1 tumor-bearing mice model to verify the effects of CCL5 and CCL3 in vivo." (PMID 41029711, 2025).
tumor (continued). "Knockdown of Ccl5 resulted in augmented tumor growth and diminished infiltration of DC." (PMID 39773173, 2025). "Furthermore, we confirmed that PDAC cells utilized LMO7 to decrease Foxp1 protein levels in vivo, promoting the secretion of TGF-β/CCL5 and Treg cell infiltration within the tumor tissue." (PMID 39143228, 2025). "Notably, while CCL5 expression was downregulated in most tumor types, it showed the highest expression levels in GBM, indicating its unique role in GBM progression." (PMID 41155216, 2025). "The N2 markers include CCL17, CCL2, Arg, CCL5, and vascular endothelial growth factor (VEGF).The role of transforming growth factor-β (TGF-β) signaling within the tumor microenvironment (TME) has been implicated in the promotion of a pro-tumorigenic neutrophil phenotype (N2)." (PMID 40160822, 2025). "Chen indicated that T cells in PDAC have enriched expression of CCL5 which could induce tumor cell migration through interaction with SDC1." (PMID 41364407, 2025). "CCR5 facilitates T cell migration to inflammatory or infectious sites by binding to chemokines like CCL3, CCL4, and CCL5, particularly crucial in anti-tumor immunity and chronic inflammation, the infiltration of CCR5+ T cells is associated with the efficacy of immunotherapy." (PMID 41438981, 2025). "Finally, this study shows that by regulating the PI3K/AKT/IRF9 pathway, ITGβ8 promotes the secretion of CCL5 in tumor cells, thereby promoting the M2 polarization of macrophages and tumor progression." (PMID 39535362, 2025). "The CCL5 expression was also examined in tumor tissues, and the results demonstrated that the proportion of CCL5+ cells was increased in the combo group and the elevation was mitigated in the combo+anti‐CCL5 group." (PMID 40995650, 2025). "Notably, regarding Fib_CD74+–CD4T_FOXP3+ MHC-I ligands (HLA-A/B/C) only exist in normal samples, while in the tumor microenvironment, Fib_CD74+ promotes the recruitment of CD4T_FOXP3+ through the binding of CCL5 to the CCR4 receptor." (PMID 40948762, 2025). "Ccl5 was reported to contribute to tumor growth in a variety of cancer types." (PMID 40282557, 2025). "Additionally, TAMs secrete chemokines, such as CCL2, CCL5, and IL-10, which recruit and induce other immunosuppressive cells, including regulatory T cells (Tregs) 24, 25, thereby further suppressing anti-tumor immune responses." (PMID 40303328, 2025). "Moreover, TCM from CCL5 knocking down based on ITGβ8 overexpression in A549 cells decreased the number of migratory and invasive tumor cells." (PMID 39535362, 2025). "We measured the concentration of CCL5 in tumor site by ELSA to confirm the knockdown efficiency." (PMID 39773173, 2025). "GABA induced a non-T cell inflammatory tumor microenvironment by inhibiting the activity and infiltration of CD8+ T cells, and it also suppressed the production of chemotactic factors, such as CCL4 and CCL5, which typically recruit T cells and dendritic cells to the tumor site." (PMID 40243466, 2025). "Both LMO2 and CCL5 promote tumor cell AR signaling reactivation via paracrine signaling." (PMID 41154598, 2025). "CAAs differ from “normal” adipocytes as they display fibroblast-like morphology, usually contain several dispersed small lipid droplets, and produce increased amounts of inflammatory cytokines IL-1β, IL-6, IL-8, TNF, chemokines (CCL2, CCL5), and leptin, which altogether facilitate tumor progression." (PMID 40940764, 2025). "Additionally, several IFN‐stimulated genes (ISGs) were upregulated, including Ccl5 and Cxcl10, which are essential chemokines for attracting tumor‐infiltrating lymphocytes (TILs), indicating activation of the type I IFN pathway." (PMID 40135833, 2025). "Additionally, NK cells secrete XCL1 and CCL5, which specifically attract cDC1s, underscoring an NK‐DC interaction that enhances tumor immune surveillance." (PMID 40667699, 2025).
tumor (continued). "Spatial transcriptomics of TAMs infiltration in NSCLC reveals that TAMs enrichment in the TME is relevant to tumor cell resistance to ICB immunotherapy regardless of its PD-L1 status, which is mediated by CD27, ITGAM, and CCL5 gene expression upregulation within tumor compartment." (PMID 40083710, 2025). "The lymphatic endothelial cells (LECs), a component of LVs within the pre-metastatic niche, can be conditioned by tumor-secreted IL-6 to express CCL5 and VEGF, which facilitate C-C chemokine receptor type 5-positive (CCR5+) tumor cell recruitment, extravasation and colonization into the niche." (PMID 40002869, 2025). "Additionally, they act as mechanosensors and contribute to tumor progression by upregulating chemokine (C-C motif) ligand 5 (CCL-5) and matrix metalloproteinases (MMPs) in response to tumor-induced pressure changes." (PMID 40606222, 2025). "In ccRCC specimens exhibiting CCL5 upregulation, a significant increase was observed in both CCL5+ tumor-associated macrophages (TAMs) and PD-L1+ CD68+ TAM populations, indicative of an immunosuppressive tumor immune microenvironment (TIME)." (PMID 40396123, 2025). "In addition, chemokines secreted at necrotic tumor sites by C-C motif chemokine ligand 2 (CCL2) and C-C motif chemokine ligand 5 (CCL5) allow for higher macrophage recruitment and infiltration in tumor tissues." (PMID 40725148, 2025). "Circulating monocytes, under the influence of chemokines like C-C motif ligand 2 (CCL2) and C-C motif ligand 5 (CCL5), are actively recruited to the tumor site, where they differentiate into macrophages and adopt pro- or anti-tumor phenotypes depending on microenvironmental cues." (PMID 40098971, 2025). "Olaparib promotes CD8+ T-cell infiltration via the cGAS/STING pathway, especially in BRCA1-deficient tumours, while increased cytosolic DNA leads to CCL5/CXCL10-driven T-cell recruitment, independent of BRCA status." (PMID 40361472, 2025). "Elevated CCL5 levels correlate with greater tumor invasiveness and immune evasion." (PMID 40868199, 2025). "Tumor−derived CXCL12 and CCL5 are known to recruit suppressive myeloid and regulatory T cells, promote tumor growth, and stimulate neoangiogenesis, whereas TGF−β directly attenuates CD8+ T cell cytotoxicity and drives exhaustion in chronic inflammatory contexts." (PMID 40948762, 2025). "Furthermore, biological function experiments revealed that CCL5 knockdown inhibited the A549‐ITGβ8‐TCM‐mediated promotion of tumor cell proliferation, migration, and invasion." (PMID 39535362, 2025). "The CCL5/CCR5 axis enhances T cell migration to the tumor site." (PMID 41438981, 2025). "Given that cisplatin-induced DNA damage may triggers mitotic catastrophe in tumor cells, we asked whether CCL5 may protect cells from this process." (PMID 41152972, 2025). "To determine whether CCL5 is specifically responsible for this effect, we supplemented recombinant CCL5 and assessed tumor cell responses to cisplatin." (PMID 41152972, 2025). "Moreover, CCL5 facilitates the migration and invasion of tumor cells through its interaction with CCR5 receptors present on these cells." (PMID 40076892, 2025). "Moreover, the expression of inflammatory chemokines potentially involved in the recruitment of cytotoxic T cells to the tumor microenvironment, like CCL5 and CCL10, was also upregulated." (PMID 39810240, 2025). "Within the tumor lysate CTX upregulated MIG but also increased RANTES (CCL5) a known macrophage recruiting cytokine, and this could potentially explain why tumors recur post CTX treatment cessation." (PMID 40568104, 2025). "Notably, CCL5 has been identified as a key player in tumor initiation and progression by facilitating immune evasion." (PMID 39859340, 2025). "Furthermore, HDAC3, as a part of the NCoR repressor complex, can suppress the expression of Cxcl10 and Ccl5 in several tumor entities, leading to T-cell and NK-cell exclusion from the TME and immunotherapy resistance." (PMID 40562773, 2025).
tumor (continued). "To this end, we first constructed the double Kmt5c and Ccl5 knockdown LLC cells to investigate whether the speed of tumor growth could be rescued compared to that in Kmt5c single knockdown LLC cells." (PMID 40126333, 2025). "However, YAP depletion concomitantly abrogated the extracellular secretion of the chemokines Ccl5 and Cxcl10, which are key targets of type-I IFNs that promote tumor infiltration and activation of CTLs." (PMID 40542295, 2025). "Furthermore, some studies have shown that FN1 and CCL5 gene expression positively correlates with immune cell infiltration within the tumor." (PMID 39245631, 2025). "Additionally, CCL5 induces metabolic reprogramming, enhances angiogenesis, and recruits normal cells to support tumour development." (PMID 40361472, 2025). "Notably, tumor cells were the exclusive source of overexpressed Ccl5 and Cxcl2, while Ccr5 + NK cells and Cxcr2 + macrophages were enriched in the NLRP4-OE TIME, a pattern that persisted throughout tumor progression." (PMID 40087771, 2025). "Moreover, tumor-conditioned monocytes from healthy donors acquired an NCM-like phenotype and displayed enhanced migration toward CCL5/CXCL12, suggesting recruitment into the tumor-associated macrophage pool." (PMID 41219641, 2025). "To investigate whether CAF-derived CCL5 mediates the protective effect of tumor cells against cisplatin treatment, we first co-cultured tumor cells with a conditioned medium obtained from CAFs and tested the cells’ response to cisplatin treatment." (PMID 41152972, 2025). "In OSCC, CCL5 is secreted by tumor or stromal cells – typically exhibits downregulation." (PMID 41445742, 2025). "CCL5 is known to be involved in immune cell recruitment and exhaustion, and may play dual roles in tumor progression." (PMID 41155216, 2025). "Eosinophils can recruit tumor-specific CD8+ T cells into the tumor microenvironment by secreting chemokines such as CCL5, CXCL9, and CXCL10, and induce macrophage polarization toward the M1 phenotype, thereby enhancing the immune system’s ability to recognize and destroy tumor cells." (PMID 39949762, 2025). "Our findings could support the idea that the increased CCL5 in specific cells serves as an effective and promising adjuvant in tumor treatment." (PMID 39773173, 2025). "CCL5 derived from TAMs promotes tumor invasion, metastasis, and the self-renewal of BCSCs." (PMID 40904511, 2025). "Additionally, IκBζ suppresses Cxcl9, Cxcl10, and Ccl5 expression via HDAC3 and EZH2, which impairs the recruitment of NK and CD8+ T cells into the tumor, causing resistance to α-PD-1 immunotherapy in mice." (PMID 40562773, 2025). "It was demonstrated that PGE2 could inhibit the recruitment of DCs into tumor via decreasing CCL5 and XCL1 produced by NK cells, which suggested ferroptosis could impair pro-inflammatory immunity through affecting on innate immune." (PMID 40064873, 2025). "Overexpression of CCR5/CCL5 axis proteins in OSCC is associated with poor outcomes, including regional lymph node metastasis and reduced overall survival, signifying a highly aggressive tumor phenotype and unfavorable prognosis." (PMID 41445742, 2025). "In another study, ginseng-derived EVs reprogram tumor-associated macrophages (TAMs), increasing the secretion of CCL5 and CXCL9 to recruit CD8+ T cells into the tumor core, thereby enhancing the efficacy of immune checkpoint blockade therapy with PD-1 monoclonal antibodies." (PMID 40630801, 2025). "The CCL5-CCR5 axis inhibitor Malawijo confirmed that the removal of tumor cell-derived CCL5 diminished ERK1/2 signaling, leading to the inhibition of ESCC cell proliferation in vitro and in vivo, as well as reducing the proportion of CAFs recruited by xenograft tumors." (PMID 40134607, 2025). "Similarly, elevated CCL5 expression correlated with higher tumor grades, supporting its potential role as a biomarker for disease progression." (PMID 40884261, 2025).